CCDC198 (coiled-coil domain containing 198)
Description:
May be involved in tuning the metabolism, energy expenditure, and excretion processes.
Synonyms: C14orf105; FAME; FLJ10650
Tractability: Antibody: UniProt places it where antibodies can reach, with high confidence; its Gene Ontology location is reachable by antibodies, with medium confidence.
Gene: Protein-coding gene on chromosome 14 (57,469,300 to 57,493,872, reverse strand). Ensembl gene ENSG00000100557.
Subcellular location: Cell membrane; Cytoplasmic vesicle
Subcellular location (Human Protein Atlas): Cytosol; Nucleoplasm
Gene Ontology:
Molecular function: protein binding
Biological process: energy homeostasis
Cellular component: plasma membrane; cytoplasmic vesicle
Genetic constraint (gnomAD): Loss-of-function variants: 12 observed, 28.11 expected, observed/expected ratio (o/e) 0.43, 90% interval 0.27 to 0.69. The upper end of that interval is the gene's LOEUF score, 0.69, which puts it in group 2 of 6, group 1 being the genes least tolerant of losing a copy. Missense variants: 282 observed, 277.24 expected, observed/expected ratio (o/e) 1.02, 90% interval 0.92 to 1.12. Synonymous variants: 91 observed, 94.89 expected, observed/expected ratio (o/e) 0.96, 90% interval 0.81 to 1.14.
Homologues: Orthologues: chimpanzee CCDC198 (98% identical), macaque CCDC198 (93% identical), dog CCDC198 (78% identical), rabbit CCDC198 (76% identical), pig CCDC198 (71% identical), guinea pig CCDC198 (68% identical), mouse Ccdc198 (63% identical), rat Ccdc198 (56% identical), tropical clawed frog ccdc198 (39% identical).